EGFR (epidermal growth factor receptor)
Diseases named in the same sentence as EGFR in open-access papers (continued):
Sharing a sentence is not in itself a finding about the gene and the disease.
lung cancer (continued). "We thus conclude that there is an unexpected but significant interdependence between the EGFR targeting siRNA sequence and the RT-qPCR amplification region for assessing the efficacy of the siRNA target gene knockdown and that this finding can be extended to other mRNAs in lung cancer cells." (PMID 21369532, 2010). "Together these findings provide strong mechanistic rationale for the clinical use of inhibitors of the c-Met pathway in combination with EGFR TKIs in treatment of lung cancer patients and may have implications in other cancers that demonstrate c-Met-EGFR cross-talk as well." (PMID 21390244, 2010). "It remains to be elucidated whether EGFR copy number and EGFR mutation status will be markers of response to these agents in the context of anal SCC as has been shown for lung cancers." (PMID 21063399, 2010). "Dual targeting of c-Met/EGFR may have clinical benefit for lung cancer." (PMID 21390244, 2010). "In addition, some solid tumors, such as lung cancer, exhibit EGFR gene amplification." (PMID 20459769, 2010). "However, molecular correlate studies in lung cancer and colon cancer, which have EGFR-targeted therapeutics FDA-approved for treatment, may provide insights." (PMID 19636423, 2009). "Other genes inhibited by EGFR signaling, such as gap junction protein alpha 1 (Gja1), a mediator for cell-cell communication in lung epithelial cells that is down-regulated in human and mouse lung cancer, were elevated in the BALB mice (Gja1, confirmed by PCR, data not shown)." (PMID 19925653, 2009). "However, we report a GW2974-sensitive lung cancer cell line (H1666) that has normal level of both Her2 and Met, and does not have activating mutation in EGFR." (PMID 19240716, 2009). "Also, the EGFR gene polymorphic simple sequence repeat (SSR) length, the Y/X polymorphism of the innate-immunity gene MBL2 with haplotypes, and glutathione-related genes have been associated with improved lung cancer survival." (PMID 19478952, 2009). "It suggested that an activation of the EGFR/PI3K/AKT/mTOR pathway could be linked to CDKN2A homozygous deletion in lung cancer regardless of smoking status." (PMID 18549475, 2008). "Our results also implicate that combination treatment using a MET inhibitor plus a reversible or irreversible EGFR kinase inhibitor to achieve dual MET–EGFR inhibition may represent an alternative strategy to circumvent T790M-EGFR-mediated resistance in lung cancer." (PMID 19238632, 2008). "Importantly, erlotinib may still have clinical utility in this context of combined inhibition with MET inhibitor in EGFR-TKI-resistant lung cancer." (PMID 19238632, 2008). "Our results, therefore, suggest that the polymorphisms of the HER-2 gene might contribute to the susceptibility of female, non-smoker and non-drinker subgroups in the Korean population to lung cancer as EGFR mutations." (PMID 19055823, 2008). "Since the data shows that hTERT and EGFR mRNA levels are associated with previously detected lung cancers, it does not demonstrate whether the method is sufficiently robust for early detection." (PMID 21892326, 2008). "However, the evaluation of hTERT mRNA combined with EGFR mRNA may be a useful biomarker to diagnose and assess the clinical stage and effect of treatments in patients with lung cancer." (PMID 21892326, 2008). "However, EGFR mutation was found to be generally rare in most malignancies except lung cancers, and gefitinib-sensitive cancers without EGFR mutations have been reported in HER2-overexpressing breast cancer cell lines as representative examples." (PMID 17088902, 2006). "The other lung cancer cell lines did not display any EGFR gene mutations in these regions." (PMID 17150102, 2006). "Likewise, the finding that a small subset of NSCLC patients who have gain-of-function epidermal growth factor receptor (EGFR) mutations and response rates to gefitinib and erlotinib of over 80% must be viewed as a major advance in our understanding of lung cancer biology." (PMID 15928656, 2005).
lung cancer (continued). "Transcriptomics analyses of EGFR TKI-resistant tumor models revealed an aberrant upregulation of S1PR3, which conferred enhanced metastatic potential to lung cancer." (PMID 42039707, 2026). "Emerging evidence indicates that activation of STAT3 is one of the contributors to EGFR-TKI resistance, and targeted inhibition of STAT3 signaling has shown potential to circumvent therapeutic resistance both in lung cancer and other malignancies." (PMID 41539998, 2026). "To test the possibility that the EGFR‐mutant tumor cells‐derived products could directly modulate DCs, we co‐cultured iDCs from healthy human blood monocytes with the conditioned medium (CM) collected from EGFR‐mutant or WT lung cancer cells and subsequently induced them to be mature with LPS." (PMID 41144813, 2026). "Nonsmall cell lung cancer (NSCLC) tumorsin particular, frequently have oncogenic drivers arising from activatingmutations in EGFR, most commonly in-frame deletion of Exon19 (Exon19del)or L858R point mutation." (PMID 41432179, 2026). "Here, we found that molecular therapy targeted toward EGFR mutant, KRAS mutant, or ALK fusion lung cancer induced cholesterol biosynthesis, which promoted cancer cells to enter dormancy and thus escape drug killing." (PMID 41983392, 2026). "More precisely, the suppression of cell growth and motility in lung cancer cells by WSG is attributed to the degradation of TGFβR and EGFR produced by WSG." (PMID 40142097, 2025). "Epidermal growth factor receptor (EGFR) is expressed in many solid tumors, including non‐small cell lung cancer, and is the origin of cancer growth signaling." (PMID 40620186, 2025). "In lung cancer, ALDOA exhibits a tumor-promoting effect through the EGFR/MAPK signaling cascade and modulation of HIF-1α signaling." (PMID 39755705, 2025). "We also evaluated the prognosis of lung cancer patients treated with EGFR tyrosine kinase inhibitors (TKI) and monoclonal antibodies (MAB) and whether in this subgroup, co-occurrence of CNVs and mutations affected prognosis compared to those having EGFR mutation alone." (PMID 41415395, 2025). "Recently, a newer generation EGFR-TKI, osimertinib, has been approved as an adjuvant treatment for early-stage EGFR-mutant lung cancer after curative resection." (PMID 40002883, 2025). "Five core targets, AKT1, EGFR, HSP90AA1, SRC, and STAT3, were identified as key mediators of its anti-lung cancer action, participating in critical signaling pathways including MAPK, PI3K-Akt, and Ras pathways." (PMID 41465428, 2025). "In lung cancer, FUCA1 can inhibit EGFR signaling and its downstream signaling by inhibiting AKT phosphorylation." (PMID 40487392, 2025). "An in vitro study using the EGFR-mutant lung cancer cell lines HCC827 and H4006 co-cultured with activated peripheral blood mononuclear cells and treated with EGFR-TKIs showed notable changes in immune cell dynamics." (PMID 40002883, 2025). "Both positive regulation of growth and regulation of growth pathways capture oncogenic signaling (e.g., EGFR, KRAS, and Hippo/YAP) that drive proliferation, metabolic adaptation, and immune evasion in lung cancer." (PMID 41228248, 2025). "The parental lung cancer cells PC9 and HCC827 were exposed to gefitinib treatment for approximately 6 months to develop EGFR-TKIs-resistant lung cancer cells PC9/Gr and HCC827/Gr." (PMID 39744423, 2025). "Using both DNA and RNA, CDx can detect most driver alterations (EGFR, ALK, ROS1, MET, KRAS, BRAF, RET) that are amenable to molecular‐targeted therapy in lung cancer." (PMID 40616301, 2025). "For the first time, the current study reported that rapamycin has a binding affinity with ALK, EGFR, FGFR, MET, and ROS1 receptors expressed in the lung cancer cells." (PMID 39762538, 2025). "After the validation of GM‐protac efficacy on the cellular function of osimertinib‐resistant lung cancer, we then further analyzed the potential mechanisms of GM‐protac on HDAC and EGFR signaling pathways in H1975‐OR cells." (PMID 40842076, 2025).
lung cancer (continued). "Collectively, these findings suggest that AKT1, EGFR, HSP90AA1, SRC, and STAT3 represent important therapeutic targets for anti-lung cancer intervention." (PMID 41465428, 2025). "In lung cancer cells, EMT impairs drug sensitivity and promotes acquired resistance to epidermal growth factor-tyrosine kinase inhibitors (EGFR-TKI)." (PMID 40746888, 2025). "In contrast, classical lung cancer‐related pathways, including the JAK‐STAT signaling pathway, PI3K‐Akt signaling pathway, EGFR tyrosine kinase inhibitor resistance, NF‐kappa B signaling pathway, and MAPK signaling pathway, were significantly activated." (PMID 40583191, 2025). "The elevated expression of CD109 was found to promote tumour metastasis and drug resistance in lung cancer via activation of EGFR-AKT-mTOR signalling pathways and aggressiveness of cervical squamous cell carcinoma with the EGFR regulation." (PMID 40227788, 2025). "Targeting EGFR-mediated signaling offers promising strategies to improve NSCLC therapies, particularly in overcoming resistance in EGFR-mutant lung cancer." (PMID 40076971, 2025). "The selective inhibition of AKR1B1, achieved through the use of epalrestat, an antidiabetic drug, restored the responsiveness of resistant cell lines to EGFR TKIs and delayed resistance in PDX mice with lung cancer." (PMID 39830019, 2025). "Erlotinib, an EGFR tyrosine kinase inhibitor, has been reported to interact with CAF in lung cancer therapy." (PMID 40226936, 2025). "The STRING protein–protein interaction (PPI) analysis of EGFR, ALK, KRAS, and PD-1 revealed a complex, yet functionally coordinated molecular landscape in lung cancer." (PMID 40927719, 2025). "In cancer, for example, statins such as lovastatin and simvastatin disrupt EGFR- or IGF1R-containing lipid rafts, and enhance the efficacy of TKIs in prostate, breast, and lung cancer models." (PMID 41369325, 2025). "Osimertinib, a third‐generation EGFR‐TKI, can overcome this resistance, significantly prolonging the survival of patients with EGFR‐mutant lung cancer." (PMID 39721017, 2025). "Examples of molecularly targeted therapies include inhibitors of mutant EGFR and ALK in lung cancers; inhibitors of BRAF in melanomas; or inhibitors of mutant EGFR and HER2 in breast cancer." (PMID 40783466, 2025). "Previous studies showed that oncogenic KRAS and activated epidermal growth factor receptor (EGFR) promoted FASN expression via ERK in pancreatic and lung cancer cells." (PMID 40621620, 2025). "AKT1, EGFR, HSP90AA1, SRC, and STAT3 exhibited the highest degree values and were identified as core therapeutic targets for lung cancer." (PMID 41465428, 2025). "In the context of lung cancer diagnostics, specific products such as ExoDx Lung (ALK), ExoDx Lung (T790M), and ExoDx Lung (EGFR) by Exosome Diagnostics Inc. facilitate sensitive, accurate, and real-time mutation detection through exosomes." (PMID 41573685, 2025). "Researchers have developed a 1-D grating-based SPR biosensor and a carboxyl-functionalized molybdenum disulfide SPR detection assay, focusing on the detection of epidermal growth factor receptor (EGFR) and carcinoembryonic antigen (CEA) lung cancer biomarkers." (PMID 40047624, 2025). "Our findings contrast with previous studies in lung cancer patients, where those with low GLI-1 expression showed significantly better progression-free survival with EGFR-TKI erlotinib treatment compared to those with high GLI-1 expression." (PMID 39971779, 2025). "With the emergence of targeted therapies such as the third-generation EGFR-TKIs and the second-generation ALK-TKIs, as well as the rise of immunotherapy, the treatment pattern of lung cancer has undergone revolutionary changes." (PMID 41002559, 2025). "In conclusion, our findings establish CAMSAP3 as a key regulator of EGFR signaling and osimertinib response in NSCLC, highlighting its therapeutic potential for overcoming drug resistance in lung cancer." (PMID 41381443, 2025).
lung cancer (continued). "CAR-T cells targeting EGFR, CEA, and MSLN have been carried out for patients with lung cancer in clinical trials." (PMID 40624569, 2025). "The aim of the current study is to investigate the prevalence of alterations in the eight most frequently altered genes in lung cancer—BRAF, EGFR, KRAS, ALK, ROS1, HER2, PD-L1 and PIK3CA." (PMID 41153394, 2025). "As EGFR was observed to be highly expressed in some NSCLC cell lines, we evaluated the expression of EGFR and PD-L1 in lung cancer cell lines HCC827 and H23, with K562 cells as a control." (PMID 41450878, 2025). "Upregulated EGFR activity is a major drug target for the treatment of solid tumours and the microtubule-dependent transport of EGFR endosomal vesicles by α-tubulin acetylation links HDAC6 to the pathogenesis of prostate, pancreatic, and lung cancer cells." (PMID 39941046, 2025). "Together, these data suggest that IL-1β blockade might be particularly effective in treating lung cancer in the presence of oncogenic driver mutations, potentially making canakinumab more effective when combined with EGFR TKIs rather than with chemotherapy or immunotherapy." (PMID 40940992, 2025). "Key advancements underscore this shift: molecularly targeted drugs (e.g., trastuzumab for HER2-positive breast cancer, EGFR and ALK inhibitors for lung cancer) have improved efficacy and reduced toxicity compared to conventional therapy." (PMID 41295218, 2025). "A series of antigens targeting surface proteins, including EGFR, CEA, MSLN, HER2, ROR1, MUC1, and DLL3 in lung carcinoma cells have been incorporated into CAR structure to allow CAR-T cells target lung cancer tissue." (PMID 40624569, 2025). "For instance, specific mutations in the EGFR gene are used as indicators for targeted therapies in non‐small cell lung cancer (NSCLC), guiding the use of EGFR inhibitors." (PMID 40636286, 2025). "Most of the studies developed models for the prediction of EGFR, followed by PD-L1 and ALK biomarkers in lung cancer." (PMID 40078179, 2025). "In some types of lung cancer, AURKA inhibitors in combination with EGFR inhibitors have been shown to provide greater tumor suppression than monotherapy." (PMID 39928563, 2025). "Collectively, our findings establish PYCR1 as a critical regulator of EGFR and TLR signaling pathways, driving lung cancer progression." (PMID 41254241, 2025). "This study adopts a structure-guided and expression-validated approach to characterize EGFR, ALK, KRAS, and PD-1—four of the most clinically actionable targets in lung cancer." (PMID 40927719, 2025). "Recently, many studies have explored the relationship between EGFR and ALK gene rearrangements and the imaging and pathological features of lung cancer, but there are many controversies." (PMID 41020204, 2025). "Herein, we investigated the role of BRG1 in EGFR-TKI response in vitro and in vivo using lung cancer models." (PMID 41514577, 2025). "Other bispecific antibodies are being investigated in the treatment of lung cancer, including molecules targeting PD1/VEGF in advanced NSCLC101 and in combination with EGFR-TKI." (PMID 40537184, 2025). "In lung cancer metastasis, lncRNAs play a significant role in RTK signalling pathways such as transforming growth factor‐β (TGF‐β), EGFR, and VEGF, contribute to metastasis." (PMID 40783798, 2025). "Some studies have reported that higher degree of sialylation and phosphorylation interactively regulate EGFR dimerization and activation in TKI-resistant EGFR mutant cells and sialidase can increase EGFR dimerization upon EGF treatment in lung cancer cells." (PMID 40154885, 2025). "Five core protein targets, AKT1, EGFR, HSP90AA1, SRC, and STAT3, were identified as potential mediators of steamed PJR’s anti-lung cancer effects." (PMID 41465428, 2025).